ZFP36 (ZFP36 zinc finger CCCH-type)
Description:
Zinc-finger RNA-binding protein that destabilizes several cytoplasmic AU-rich element (ARE)-containing mRNA transcripts by promoting their poly(A) tail removal or deadenylation, and hence provide a mechanism for attenuating protein synthesis. Acts as an 3'-untranslated region (UTR) ARE mRNA-binding adapter protein to communicate signaling events to the mRNA decay machinery. Recruits deadenylase CNOT7 (and probably the CCR4-NOT complex) via association with CNOT1, and hence promotes ARE-mediated mRNA deadenylation. Functions also by recruiting components of the cytoplasmic RNA decay machinery to the bound ARE-containing mRNAs. Self regulates by destabilizing its own mRNA. Binds to 3'-UTR ARE of numerous mRNAs and of its own mRNA. Plays a role in anti-inflammatory responses; suppresses tumor necrosis factor (TNF)-alpha production by stimulating ARE-mediated TNF mRNA decay and several other inflammatory ARE-containing mRNAs in interferon (IFN)- and/or lipopolysaccharide (LPS)- induced macrophages (By similarity). Also plays a role in the regulation of dendritic cell maturation at the post-transcriptional level, and hence operates as part of a negative feedback loop to limit the inflammatory response. Promotes ARE-mediated mRNA decay of hypoxia-inducible factor HIF1A mRNA during the response of endothelial cells to hypoxia. Positively regulates early adipogenesis of preadipocytes by promoting ARE-mediated mRNA decay of immediate early genes (IEGs) (By similarity). Negatively regulates hematopoietic/erythroid cell differentiation by promoting ARE-mediated mRNA decay of the transcription factor STAT5B mRNA. Plays a role in maintaining skeletal muscle satellite cell quiescence by promoting ARE-mediated mRNA decay of the myogenic determination factor MYOD1 mRNA (By similarity). Associates also with and regulates the expression of non-ARE-containing target mRNAs at the post-transcriptional level, such as MHC class I mRNAs. Participates in association with argonaute RISC catalytic components in the ARE-mediated mRNA decay mechanism; assists microRNA (miRNA) targeting ARE-containing mRNAs. May also play a role in the regulation of cytoplasmic mRNA decapping; enhances decapping of ARE-containing RNAs, in vitro. Involved in the delivery of target ARE-mRNAs to processing bodies (PBs). In addition to its cytosolic mRNA-decay function, affects nuclear pre-mRNA processing (By similarity). Negatively regulates nuclear poly(A)-binding protein PABPN1-stimulated polyadenylation activity on ARE-containing pre-mRNA during LPS-stimulated macrophages (By similarity). Also involved in the regulation of stress granule (SG) and P-body (PB) formation and fusion (By similarity). Plays a role in the regulation of keratinocyte proliferation, differentiation and apoptosis. Plays a role as a tumor suppressor by inhibiting cell proliferation in breast cancer cells. (Microbial infection) Negatively regulates HTLV-1 TAX-dependent transactivation of viral long terminal repeat (LTR) promoter.
Synonyms: Zfp-36; G0S24; NUP475; RNF162A; TTP; TIS11; GOS24
Tractability: PROTAC: UniProt records ubiquitination sites on it; ubiquitination databases record sites on it.
Gene: Protein-coding gene on chromosome 19 (39,406,847 to 39,409,407, forward strand). Ensembl gene ENSG00000128016.
Subcellular location: Nucleus; Cytoplasm; Cytoplasmic granule; Cytoplasm, P-body
Subcellular location (Human Protein Atlas): Intermediate filaments
Pathways (Reactome):
Metabolism of RNA: Tristetraprolin (TTP, ZFP36) binds and destabilizes mRNA
Gene Ontology:
Molecular function: 14-3-3 protein binding; C-C chemokine binding; enzyme binding; heat shock protein binding; mRNA 3'-UTR AU-rich region binding; mRNA binding; protein binding; protein kinase binding; protein-containing complex binding; protein-RNA sequence-specific adaptor activity; RNA binding; mRNA regulatory element binding translation repressor activity; RNA polymerase binding; metal ion binding; mRNA 3'-UTR binding
Biological process: 3'-UTR-mediated mRNA destabilization; 3'-UTR-mediated mRNA stabilization; cellular response to epidermal growth factor stimulus; cellular response to fibroblast growth factor stimulus; cellular response to glucocorticoid stimulus; cellular response to granulocyte macrophage colony-stimulating factor stimulus; cellular response to lipopolysaccharide; cellular response to tumor necrosis factor; MAPK cascade; mRNA catabolic process; mRNA transport; negative regulation of 3'-UTR-mediated mRNA stabilization; negative regulation of cytokine production involved in inflammatory response; negative regulation of erythrocyte differentiation; negative regulation of transcription by RNA polymerase II; negative regulation of viral transcription; nuclear-transcribed mRNA catabolic process, deadenylation-dependent decay; nuclear-transcribed mRNA catabolic process, deadenylation-independent decay; nuclear-transcribed mRNA poly(A) tail shortening; positive regulation of deadenylation-independent decapping of nuclear-transcribed mRNA; positive regulation of intracellular mRNA localization; positive regulation of miRNA-mediated gene silencing; positive regulation of nuclear-transcribed mRNA catabolic process, deadenylation-dependent decay; positive regulation of nuclear-transcribed mRNA poly(A) tail shortening; regulation of keratinocyte apoptotic process; and 12 more
Cellular component: cytoplasm; cytoplasmic stress granule; cytosol; exosome (RNase complex); nucleus; P-body; ribonucleoprotein complex; CCR4-NOT complex
Genetic constraint (gnomAD): Loss-of-function variants: 13 observed, 19.96 expected, observed/expected ratio (o/e) 0.65, 90% interval 0.42 to 1.04. The upper end of that interval is the gene's LOEUF score, 1.04, which puts it in group 4 of 6, group 1 being the genes least tolerant of losing a copy. Missense variants: 354 observed, 438.05 expected, observed/expected ratio (o/e) 0.81, 90% interval 0.74 to 0.88. Synonymous variants: 191 observed, 193.08 expected, observed/expected ratio (o/e) 0.99, 90% interval 0.88 to 1.12.
Homologues: Orthologues: chimpanzee ZFP36 (99% identical), macaque ZFP36 (98% identical), pig ZFP36 (90% identical), dog ZFP36 (87% identical), guinea pig ZFP36 (86% identical), rat Zfp36 (85% identical), rabbit ZFP36 (83% identical), mouse Zfp36 (81% identical), tropical clawed frog zfp36 (42% identical), Caenorhabditis elegans ccch-1 (29% identical), Drosophila melanogaster Tis11 (29% identical), Caenorhabditis elegans gla-3 (22% identical), and 18 more. Paralogues in human: ZFP36L2 (35% identical), ZFP36L1 (32% identical).
Diseases named in the same sentence as ZFP36 in open-access papers:
ZFP36 is named in the same sentence as 134 diseases in open-access papers, as found by Europe PMC text mining. Sharing a sentence is not in itself a finding about the gene and the disease. The quoted sentences say what the papers report.
breast carcinoma (20 papers, 2013 to 2025). "The hub-protein ZFP36 is associated with breast cancer and tumor-suppressive actions during hepatic tumor progression." (PMID 35277538, 2022). "ZFP36*2 has been proved to be a potential biomarker in Caucasian breast cancer patients while ZFP36*8 has been found high associated with HER2-positive-breast cancer." (PMID 34026612, 2021). "Low ZFP36 expression levels were associated with poor prognosis in breast cancer patients." (PMID 39026155, 2024). "Consistently, tumors from breast cancer patients with low butyric acid displayed lower ZFP36 mRNA and higher LRP5/NANOG/SOX2/Ki67 mRNA compared with patients with high butyric acid." (PMID 40038255, 2025). "Recently, it was shown that metformin induces ZFP36 expression through AMPK activation in breast cancer cell lines." (PMID 39026155, 2024). "The loss of RBP ZFP36 function leads to ARE-mRNA stabilization in a variety of human cancers such as prostate cancer, pancreatic cancer, breast cancer, colorectal cancer, malignant melanoma, hepatocellular carcinoma (HCC), malignant glioma, and lung cancer." (PMID 37587140, 2023). "The effect of lapatinib on the abundance of phosphorylated ZFP36/TTP was also demonstrated with another ERBB2-positive breast cancer cell line, BT-474." (PMID 34535639, 2021). "We found that ZFP36/TTP was phosphorylated mainly in breast cancer cell lines, including ERBB2-amplified SKBR3, and demonstrated that lapatinib—also ERBB2 siRNA-reduced the abundance of the phosphorylated ZFP36/TTP in a dose-dependent manner." (PMID 34535639, 2021). "In the 0.5 and 1.5 μM BD-treated MCF-7 breast cancer cells, the expression levels of ZFP36 and EGR1 were markedly increased compared with DMSO-treated." (PMID 32714860, 2020). "In addition, PROGgeneV2 analyses indicated that high expression of ZFP36 predicted a good overall survival in breast cancer patients." (PMID 40038255, 2025). "However, as pointed out previously, the relevance of TTP/ZFP36 mRNA level for breast cancer prognosis is debatable." (PMID 38274271, 2023). "However, “Claudin-Low” breast cancers, which present stem-like expression profiles, displayed significantly higher ZFP36 expression levels than Luminal, Her2 and Basal subtypes." (PMID 38274271, 2023). "Furthermore, using METABRIC data, we found positive correlations between expression of ZFP36 and genes associated with the stem-like phenotype, as TWIST1, TWIST2, SNAI1, ZEB1, ZEB2, ALDH1A and YAP1 in all breast cancer subtypes." (PMID 38274271, 2023). "In conclusion, these findings revealed potential molecular mechanisms of BD to treat breast cancer by affecting AMIT_SERUM_RESPONSE_40_MCF10A, BILD_HRAS_ONCOGENIC_SIGNATURE, and NAGASHIMA_NRG1_SIGNALING_UP pathways and regulating expression of ZFP36, EGR1, and FOS." (PMID 32714860, 2020). "In breast cancer, ZFP36 gene defects will contribute to cancer progression and development." (PMID 32714860, 2020). "MiR‐423 has been proved to be an oncogene that promotes the malignant breast cancer (BC) cells proliferation and migration, can inhibit the expression of ZFP36 in BC cells, and activate Wnt/β‐catenin signaling pathway, ultimately affecting the chemoresistance and apoptosis rate of BC cells." (PMID 33174687, 2020). "While no ZFP36 mutations have been reported as direct genetic link to cancer incidence, specific ZFP36 polymorphisms are associated with breast cancer survival." (PMID 26343742, 2015). "Furthermore, zinc finger protein 36 (ZFP36) is correlated with lower-tumour grade breast cancer." (PMID 36661191, 2023). "Therefore, we elucidated a novel mechanism for how MBNL1-AS1 regulated the phenotype of BC and targeting the MBNL1-AS1/ZFP36/CENPA axis might function as therapeutic targets for breast cancer patients." (PMID 35518784, 2022).
breast carcinoma (continued). "The results showed BD in breast cancer treatment may take actions through affecting AMIT_SERUM_RESPONSE_40_MCF10A, BILD_HRAS_ONCOGENIC_SIGNATURE, and NAGASHIMA_NRG1_SIGNALING_UP pathways and regulation expression of ZFP36, EGR1, and FOS(c-FOS)." (PMID 32714860, 2020). "In addition, HADS scores were negatively correlated with ZFP36 expression and positively related with LRP5, β-catenin and NANOG expression in cohort 1 breast cancer patients." (PMID 40038255, 2025). "Meanwhile, the results of in vivo assays also confirmed that transfection of MBNL1-AS1 or si-MBNL1-AS1 did not revert the tumorigenic abilities after ZFP36 knockdown in orthotopic breast cancer mice models." (PMID 35518784, 2022). "Our results showed that BD could significantly increase ZFP36 mRNA and protein expression in a dose-dependent manner in MCF-7 and MDA-MB-231 breast cancer cells." (PMID 32714860, 2020). "Simultaneously, the key genes, including ZFP36, EGR1, and FOS may be potentially effective targets of BD and also are crucial for breast cancer development." (PMID 32714860, 2020). "The over-expressed CCNE1, CLGN, NEK2, PTTG1 and RAD51, and the under-expressed ADAMTS1, FOS, FOSB, IL6 and ZFP36 in tumor cells are examples of breast cancer genes without differential promoter methylation between normal and tumor samples." (PMID 25706888, 2015). "At three concentration of BD, 0.1, 0.5, and 1.5 μM, the expression of ZFP36 and EGR1 mRNA were increased in MCF-7 and MDA-MB-231 cells in a dose-dependent manner, while the level of FOS mRNA was significantly reduced in a concentration-dependent manner in MCF-7 and MDA-MB-231 breast cancer cells." (PMID 32714860, 2020).
hepatocellular carcinoma (16 papers, 2012 to 2025). A malignant tumor that arises from hepatocytes. "Recently, it has been shown that increased DNA methylation of a single CpG site in the ZFP36 promoter in hepatocellular carcinoma (HCC) is responsible for TTP loss." (PMID 26343742, 2015). "We also assessed temporality of ZFP36 induction in the hepatocellular carcinoma (HCC) cell response to serum, bone marrow-derived macrophage (BMDM) response to lipopolysaccharide (LPS), and human umbilical vein endothelial cell (HUVEC) response to VEGF." (PMID 37086408, 2023). "In hepatocellular carcinoma cell lines, hypermethylation of the Zfp36 promoter favors tumor growth, whereas in glioma cell lines, hyperphosphorylated forms of TTP predominate, increasing VEGF and IL8 mRNA stability." (PMID 33497366, 2021). "The suppression of EMT by ZFP36 is a recurring pattern in other cancers, such as ovarian cancer, hepatocellular carcinoma, and lung cancer." (PMID 34238924, 2021). "Future studies examining the link between dysregulated expression of ZFP36 and liver cirrhosis and hepatocellular carcinoma will thus provide critical information regarding the therapeutic value of targeting ZFP36 in chronic HBV infection." (PMID 22428029, 2012). "However, a recent study on the mechanism of action of ZFP36 in hepatocellular carcinoma seems to suggest the complexity of ZFP36 in the mechanism of tumor action." (PMID 40650680, 2025). "Interestingly, Zfp36 exerts influence in the treatment of hepatocellular carcinoma by regulating PRC1, while it also plays an anti-tumor role through the knockdown of Zfp36 expression to affect inflammation, metabolism and cell proliferation." (PMID 35923893, 2022). "In hepatocellular carcinoma (HCC), ZFP36 functions as a tumor suppressor by destabilizing oncogenic mRNAs such as PRC1, CCND1, and CDK6, which are implicated in cell cycle progression and tumor growth." (PMID 40361912, 2025).
Autoimmunity (11 papers, 2015 to 2025). The occurrence of an immune reaction against the organism's own cells or tissues. "Mice with disrupted Zfp36 expression have been shown to develop severe arthritis, autoimmunity, cachexia, dermatitis, and myeloid hyperplasia, due to the overexpression of TNF-α." (PMID 39684798, 2024). "Recently, it was determined that ZFP36 also plays a role in regulating T cell homeostasis and autoimmunity." (PMID 37535204, 2024). "Disruption of the gene that codes for TTP (Zfp36) led to severe arthritis, autoimmunity, cachexia and dermatitis in mice." (PMID 38274271, 2023). "Defects in ZFP36 TZF increased the stability of TNF-α mRNA and subsequently caused inflammation through the overproduction of TNF-α45; therefore, defects in ZFP36 TZF can lead to a systemic inflammatory syndrome and autoimmunity in mice." (PMID 29426877, 2018). "Importantly, the enhanced anti-viral response in the chronic absence of ZFP36 in KO mice is accompanied by spontaneous inflammation and autoimmunity that worsen with age." (PMID 29848443, 2018). "However, this role does not fully account for ZFP36 function in vivo, as underscored by reports that myeloid-specific deletions of Zfp36 do not recapitulate spontaneous autoimmunity." (PMID 29848443, 2018). "Zfp36−/− mice lacking TTP protein have a severe, pervasive inflammatory phenotype that includes cachexia, dermatitis, autoimmunity, and inflammatory arthritis." (PMID 26002976, 2015). "Moreover, ZFP36−/− mice, lacking TTP protein, have a severe inflammatory phenotype that includes cachexia, dermatitis, autoimmunity, and inflammatory arthritis, while enhanced stability of TTP mRNA protects mice from imiquimod-induced dermatitis." (PMID 33585499, 2020).
liver fibrosis (10 papers, 2021 to 2025). "In the case of ZFP36, although its role in ferroptosis regulation in liver fibrosis is well-documented, its association with diabetic kidney disease remains poorly understood and requires further investigation." (PMID 37988198, 2023). "It was reported that RNA-binding protein ZFP36 suppressed ferroptosis by regulating autophagy and was identified as the therapeutic target of liver fibrosis." (PMID 35211472, 2022). "Recently, FBXW7 has been shown to degrade ZFP36 to regulate sorafenib-induced ferroptosis, revealing that ferroptosis is a therapeutic target for liver fibrosis." (PMID 34869326, 2021). "ZFP36, regulating cell response to lipid peroxidation and oxidative stress, can lead to resistance to ferroptosis when overexpressed in liver fibrosis." (PMID 33727924, 2021). "Therefore, erastin and sorafenib treatment can ameliorate liver fibrosis by downregulating ZFP36, activating ferritinophagy, and ferroptosis in HSCs." (PMID 36703745, 2022). "Sorafenib and erastin, two ferroptosis inducers, markedly reduce hepatic fibrosis in mice subjected to a bile duct ligation and the overexpression of TTP in HSCs (through vitamin A-coupled liposomes bearing Zfp36 plasmid) strongly reduces this beneficial effect." (PMID 39941720, 2025). "ZFP36 ring finger protein (ZFP36/TTP) promotes ferroptosis in HSCs and may serve as a potential new target for the treatment of liver fibrosis." (PMID 40249927, 2025).